TNF (tumor necrosis factor)
Diseases named in the same sentence as TNF in open-access papers (continued):
Sharing a sentence is not in itself a finding about the gene and the disease.
viral infection (continued). "Measurements of other key cytokines involved in T effector functions during viral infections, such as tumor necrosis factor alpha and granzyme B,24 might further validate the efficacy of the T-cell response observed in DS after primary SARS-CoV-2 vaccination." (PMID 41196011, 2025). "Additionally, metformin enhances the production of interferons and other cytokines, such as interleukin-6 (IL-6) and tumor necrosis factor-alpha (TNF-α), which play essential roles in the innate immune response to viral infection and chronic diseases." (PMID 39772244, 2024). "In the case of viral infection, most acute viral infections may transiently alter hematopoiesis through the action of different mediators (e.g., type I IFNs and TNF-a) as reported for lymphocytic choriomeningitis virus (LCMV) and influenza infections." (PMID 39012145, 2024). "We measured production of IFN-γ and TNFα, each of which can exert antiviral effects and which, when both produced by the same cells, indicate polyfunctionality that correlates with protective capacity against virus infection." (PMID 38543790, 2024). "Additionally, we found that secondary viral infection caused a significant upregulation of TNF-α, IL-6, and IFN-β in lung and brain tissues compared to bacterial or viral infections alone." (PMID 40303164, 2024). "Indeed, cytokines such as IL-1β, IL-6 and TNF were shown to be produced in the brain itself following peripheral viral infection, most notably by microglia." (PMID 39107476, 2024). "However, treatment of mice with TAPI-2, anti-TNF-α antibody, or DNase I had a limited, but significant, effect on increasing survival after the Delta P80 virus infection." (PMID 39652608, 2024). "The production of inflammatory cytokines in the target tissue is part of the innate immune response to viral infection, the levels of cytokines (interleukin (IL)-6, IL-8, Tumor necrosis factor (TNF)-α, and interferon (IFN)-α) in the jejunum and colon of piglets were detected using the qRT-PCR." (PMID 38349151, 2024). "In addition, MyD88 KO mice, which were resistant to the Delta P80 virus infection, exacerbated the disease after intranasal administration of TNF-α at 2 days p.i.." (PMID 39652608, 2024). "Therefore, GSDME possesses the ability to regulate apoptosis and pyroptosis in response to caspase 3 activators, including chemotherapeutic drugs, tumor necrosis factor, and viral infection." (PMID 38388468, 2024). "This viral infection triggers an exaggerated immune response, often referred to as a cytokine storm, characterized by the excessive release of pro-inflammatory cytokines such as IL-6, IL-1β, and TNF-α." (PMID 39272485, 2024). "Given the importance of IL-6, TNF-α, IL-12p40, IL-23, and IL-27 in aiding the immune system during viral infection and supporting viral immunity, a fermentate that can enhance these cytokines could indeed be beneficial." (PMID 39123583, 2024). "Its synthesis is stimulated by type I and type III interferons (IFNs), lipopolysaccharides of the bacterial wall, viral infections, the Toll-like receptor agonists, polyI:C (synthetic analogue of dsRNA), tumor necrosis factor alpha (TNF-α), and genotoxic stress." (PMID 38791035, 2024). "For instance, electrochemical nanobiosensors could be integrated into Lung-on-Chip models to monitor cytokines like IL-6 or TNF-α during a viral infection." (PMID 39589620, 2024). "Subsequently, both TNF and the viral infection itself may synergistically stimulate the IKKβ-mediated phosphorylation of FAT10, with a mitigating outcome on IFN-I secretion." (PMID 37940187, 2024). "Moreover, the administration of VO extract reduced the release of inflammatory cytokines (TNF-α, IL-1β and IL-6) triggered by viral infection to a level comparable to that of the Control group." (PMID 37108306, 2023).
viral infection (continued). "The reason for the vascular leakage in DHF patients is the massive release of pro-inflammatory cytokines and chemokines upon viral infection, such as interleukin-6 (IL-6), IL-8, IL-1β, vascular endothelial growth factor, and tumor necrosis factor-α (TNF-α), leading to endothelial cell damage." (PMID 37112864, 2023). "However, subsequent virus infection of TNF-α treated cells demonstrated a significant increase of IL-1 β, IFN-γ, and TNF-α after 8 h measured on the protein levels." (PMID 37163429, 2023). "To test this hypothesis, we examined the effect of EC juice (E-juice) on TRAIL/TNF alpha release and viral infection and tested the role of TRAIL in IAV infection in E-juice exposed PCLS." (PMID 36901724, 2023). "TNF-producing Treg have been also identified in other viral infections, such as hepatitis A virus." (PMID 36969259, 2023). "In viral infections, interferon gamma inhibits tumor necrosis factor alpha—induced upregulation of endocan expression and these results likely reflect pathophysiological differences in endothelial injury in severe viral infections compared with severe bacterial infections." (PMID 38102316, 2023). "Environmental triggers such as viral infection or danger signals are recognized by monocytes, resulting in the activation of inflammatory pathways and over-production of cytokines, including IL-1β, IL-6, IL-18, and TNF." (PMID 38124139, 2023). "Indeed, in addition to the activity against viral infection, both GlcNAc and GlcNAc-NPs also decreased the expression level of IL-6, IL-8 and TNF-α mediators during IAV infection, indicating that it also possesses an anti-inflammatory effect." (PMID 36982205, 2023). "Collectively, these data support the neutralization of IFN-γ and TNF, or IL-1β in the post-acute stage of viral infection as viable therapeutic options to augment alveolar regeneration and dampen fibrotic sequelae observed following respiratory viral infections." (PMID 38077031, 2023). "It was possible that TNF-α, one of the first cytokines produced in response to viral infection, could trigger pro-inflammatory cascades, including IL-1β." (PMID 37048441, 2023). "Nevertheless, seizures could be additionally explained by the more widespread effect of IL-6 and TNF-α produced by macrophages in response to viral infection in the CNS." (PMID 37363223, 2023). "Moreover, viral infections can trigger the release of pro-inflammatory cytokines, such as interleukin-1 beta (IL-1β) and TNF, which further contribute to beta cell damage and dysfunction." (PMID 38239343, 2023). "Thus, early inflammation seems to contribute to viral infection control; however, TNF-a levels are reduced in all later time points of the NNV infection." (PMID 38068937, 2023). "In addition, TREM-2 also promotes TH1 cytokine IFN-gamma and TNF-α production to defend against virus infection." (PMID 36851564, 2023). "TNF-α may induce apoptosis of various types of cells under pathological conditions such as viral infection." (PMID 36901724, 2023). "However, the levels of TNF produced during an acute viral infection are likely to be different to those during a chronic inflammatory condition." (PMID 36851532, 2023). "A screening prior to the beginning of the TNF‐alpha inhibitor therapy should be strongly considered, as the initiation of during an active virus infection could be fatal for the patent." (PMID 36751314, 2023). "As a key cytokine in the pathogenesis of inflammation, TNF was involved in viral infection." (PMID 37808322, 2023). "Although CD4+ and CD8+ T lymphocytes have been shown to play major roles in controlling the viral infection through release of cytokines such as TNF-α or direct cytotoxicity, the complete function of these cells during DENV infections remains to be further investigated." (PMID 37457689, 2023).
viral infection (continued). "We also challenged mice with polyinosinic-polycytidylic acid (Poly(I:C)) and tumor necrosis factor α (TNF-α) to investigate the potential effects of viral infection and proinflammatory cytokine, respectively, to broaden our understanding of the effects of systemic inflammation in the pituitary." (PMID 38109308, 2023). "To explore the effect of SPJ treatment on cytokine expression, we used real‐time PCR and observed that viral infection led to increased expression of cytokines and chemokines, including IL‐6, IL‐1β, TNF‐α, IL‐10, IFN‐α, IFN‐β, and IFN‐γ, as well as CXCL‐2, CXCL‐10, CCL‐2, CCL‐3, and CCL‐5." (PMID 37544014, 2023). "TNF-α is essential for protecting hosts from acute virus infections." (PMID 37047115, 2023). "Therefore, SMYD2 inhibits the production of IFN-I and proinflammatory cytokines IL-6 and TNF-α in immune cells upon viral infection." (PMID 37673879, 2023). "Cytokines are crucial in combating viral infection and are involved in the regulation of immune and inflammatory responses, including interleukin 1β (IL-1β), interleukin-6 (IL-6) and tumor necrosis factor alpha (TNF-α)." (PMID 36146669, 2022). "These phenomena could be due to the fact that DVP-1 strengthened the organic immunity by stimulating the TLR4/MyD88/NF-κB signaling pathway by which more cytokines, such as IL-1β, IL-4, IL-6, and TNF-α, were generated and released before the viral infection." (PMID 36177044, 2022). "ICAM-1 expression is constitutively low at the surface of ECs and may be upregulated in response to stimuli, such as viral infection, oxidative stress, and pro-inflammatory cytokines, including interleukin-1β (IL1β), TNF-α, and interferon-γ (IFN-γ)." (PMID 35062347, 2022). "In contrast to IKKi induction following viral infection alone, infection of skin fibroblasts with hPIV3 in the presence of TNF led to a sustained increase in IKKi protein expression in P1 skin fibroblasts compared with fibroblasts from healthy controls and P4 (NEMO-C417R)." (PMID 35289316, 2022). "IL-1, IL-6 and TNFα are three main pro-inflammatory cytokines that are produced by endothelial and epithelial cells, macrophages and mast cells during innate immune response against viral infection." (PMID 35500008, 2022). "Many studies have demonstrated that the mechanisms of apoptosis and necroptosis are related to TNF-α in viral infections and tumours and promote a treatment target of TNF-α for these diseases; however, in parasitic diseases much is still unknown." (PMID 33683530, 2022). "Signaling pathways included virus infection, TNF, IL-17, and cancer pathways." (PMID 35528163, 2022). "The neutralizing of CXCR3 decreases TNF-α-mediated BBB damage during viral infection." (PMID 35604176, 2022). "Through induction of IFN-gamma IL-18 primes mononuclear phagocytes for TNF-alpha-induced IL-6 expression, which might be particularly relevant during the later stages of viral infection." (PMID 35860660, 2022). "In addition to interferon, viral infection induces the release of pro-inflammatory cytokines, such as interleukins (IL) and tumor necrosis factor (TNF) alpha by epithelial cells." (PMID 36143044, 2022). "Our findings demonstrated that DSV blocks the interaction of viral S protein with ACE 2, thereby downregulating the virus infection-induced pro-inflammatory cytokines (IL-6), (IL-1β), and (TNF-α) which are highly elevated instigating the innate anti-viral response." (PMID 36386162, 2022). "TNF was reported to regulate viral infection in many studies." (PMID 36422594, 2022). "In particular, the expression of cytokines IL-1β, IL-6, and TNF-α was higher than that of the regulatory cytokine IL-10, resembling a cytokine profile characteristic of M1 phenotype, which typically intervene in counteracting bacterial and viral infections." (PMID 36016576, 2022). "The endogenous TNF-α also has an essential role in protecting viral infection; therefore, some systemic toxicity may be avoided." (PMID 35268699, 2022).
viral infection (continued). "In general, most acute viral infections may transiently alter hematopoiesis through the action of different mediators (e.g. type I IFNs, TNF-a, and lymphotoxin) as reported for influenza and lymphocytic choriomeningitis virus (LCMV) infections." (PMID 35284964, 2022). "Pathway analysis suggested that Triptolide regulates the activation of mainly included PI3K-Akt signalling pathway, multiple virus infections, chemokine signalling pathway, apoptosis signalling pathway, TNF signalling pathway, and IL-17 signalling pathway in CTD-ILD." (PMID 35132912, 2022). "Accompanying an increased production of TNF-α peak evidenced in patients with virus infection, the synergism of TNF-α and IFN-γ releasing during the disease course induces PANoptosis and perpetuates a cytokine storm to cause tissue (multi-organ) damage and inflammation." (PMID 35602592, 2022). "Several necroptotic inducers comprise tumor necrosis factor α (TNFα), the CD95 receptor/Fas ligand complex, and other members of the TNF superfamily and small molecules causing serious cell stress, etoposide, and viral infections." (PMID 35813208, 2022). "For example, most of the viral infections or neurological diseases show elevated levels of TNFα." (PMID 34858132, 2021). "Indeed, it has been shown that CMV-specific CD8+ T-cells that produce IFN-γ and TNF-α as well as express CD107a play an important role in controlling this viral infection in the context of allogeneic stem cell transplantation." (PMID 34576140, 2021). "This means that if TNF-α participates in the inflammatory cascade, which results in lung injury in virus infection, then TNF-α inhibition could have the potential to dramatically reduce this lung damage." (PMID 34938746, 2021). "After viral infection, mice deficient in CXXC5 or – to a lesser extent – in Tet2 fail to show an early IFN response, and the related production of IFNα/β, CCL-5, tumor necrosis factor (TNF), and IL-12 is attenuated." (PMID 34222235, 2021). "In our study, infection with WT SARS-CoV-2, and Gamma and Zeta variants induced IL-6 and TNF production in nonimmunized mice and variable expression levels according to lineage, reinforcing the different susceptibility of mice to viral infection." (PMID 34960708, 2021). "The addition of extraneous TNF to BMDM did not alter susceptibility of cells to mutant virus infection." (PMID 34578288, 2021). "TNFα contributes to an efficient DCs maturation during virus infection, suggesting that DCs in culture can consume self-produced TNFα, which could partially explain this observation." (PMID 34943787, 2021). "Also, we performed ELISA experiments to characterize the change in levels of TREM-1 downstream cytokines, and the results proved that IL-6, IL-8, TNF-α, and others were indeed upregulated in response to viral infection." (PMID 34887856, 2021). "Additionally, stimulated splenocytes derived from ARPV/ZIKV-immunized mice produced significantly more cytokines associated with viral infection than control groups at both 8 dpi and 35 dpi, with notable increases in IL-2, IFN-γ and TNF-α." (PMID 34696250, 2021). "In early viral infection, TNF-α serves as the primary inflammatory molecule." (PMID 33440894, 2021). "Two other crucial cytokines, IL-6 and TNF-α, which generated in abundance by IL-1β stimulation or autocrined from the activated “mononuclear-macrophage system”, are elevated not only in bacterial infection but also during viral infection." (PMID 34059076, 2021). "Viral infection of host cells triggers the innate immune response, which explicates through the release of cytokines such as tumor necrosis factor-α (TNF α), granulocyte–macrophage colony-stimulating factor (GM-CSF), Interleukin-(IL-1), IL-6, and Interferon (IFN)-γ." (PMID 34944610, 2021). "The higher correlation with TNF-α may highlight the importance of host-microbe dynamics in sinus mucosa and/or imply a protective effect against viral infection." (PMID 33928889, 2021).
viral infection (continued). "To examine whether the upregulation of TNF-α plays a role in viral infection, we assessed the expression of ACE2 and the TMPRSS2, the viral entry receptor proteins involved in the spike protein (S-protein) priming." (PMID 34576032, 2021). "It has been shown that these viral infections could lead to systemic inflammation with a high level of IL-6, IL-1β, and TNFα." (PMID 33607952, 2021). "Additionally, compared to control fish, viral infection led to changes in host cell transcription of several inflammatory cytokines, including TNFα, IL1, LITAF, TLR18, and NFκB." (PMID 34185811, 2021). "Moreover, during viral infection, the virus regulates expression of inflammatory mediators such as tumor necrosis factor (TNF)." (PMID 34515981, 2021). "Overall, both IL-6 and TNF-α are major contributing factors to the development of cytokine storms as well as neurological and cardiovascular pathologies characteristic of viral infections such as COVID-related medical conditions, and therefore they are important targets for immunomodulatory therapy." (PMID 34502130, 2021). "This study demonstrated that the synergistic effect between DENV2 infection and TNF-α induction could demolish moesin expression, redistribute vinculin, and reorganize the actin cytoskeleton during virus infection." (PMID 34696472, 2021). "Doxycycline may also exert anti-inflammatory effect in patients with viral infection by inhibiting pro-inflammatory cytokines, including IL-6 and tumor necrosis factor (TNF)-α." (PMID 34020659, 2021). "Similarly, TNF-α is a cytokine produced by activated microglia and macrophages, which initiate protective responses against certain viral infections, including TMEV infection." (PMID 34893671, 2021). "Once the viral infection induces the inflammatory defense response, TNF-a could be stimulated by activated neutrophils and lymphocyte and exerted a synergistic effect in the secretion of other cytokines." (PMID 34488665, 2021). "Endothelial injury may be due to direct viral infection of endothelial cells as well as to endothelial activation and apoptosis from inflammatory cytokines, especially tumor necrosis factor alpha (TNFα)." (PMID 32423059, 2020). "Therefore, the intimate relationship between viral infection, IFN/TNF/IL-6R/STAT1expression, and the associated signaling pathway is valuable in elucidating the mechanism of virus-associating CRC." (PMID 32258125, 2020). "Another pro-inflammatory cytokine TNF-α (tumor necrosis factor-α) induces Tau phosphorylation at specific epitope pT231, a pretangle-associated epitope, whereas on the secretion of IFN-γ, which is released on viral infection, causes dephosphorylation of Tau occurring at pretangle-related epitopes." (PMID 32209097, 2020). "When macrophages and DCs fail to galvanize and educate T-cell and B-cell activation, they continue to aberrantly secrete cytokines such as IL-6 and TNFα in efforts to control viral infection, however this results in cascading inflammation, eventually resulting in cytokine storm." (PMID 32760409, 2020). "This study also identified six additional patients on TNF-alpha inhibitors who had received either the yellow fever or oral typhoid vaccine (i.e., live-attenuated vaccines) and one patient on ustekinumab (IL12/23 inhibitor) who had received the yellow fever vaccine." (PMID 32258339, 2020). "We tested the ability of HLCs to respond to ligands for PRRs (RIG-I/MDA5; TLR3, 7, 9); type I IFN, the principle activator of innate anti-viral genes; type III IFN, the main IFN expressed in hepatocytes upon viral infection; and TNF-α, an inflammatory cytokine produced early in viral infection." (PMID 32481600, 2020). "The coded protein is upregulated in reaction to viral infection and may be involved in the intercession of tumor necrosis factor (TNF)-α pro-inflammatory responses." (PMID 33101175, 2020).